SLC39A3 (solute carrier family 39 member 3)
Description:
Transporter for the divalent cation Zn(2+). Mediates the influx of Zn(2+) into cells from extracellular space. Controls Zn(2+) accumulation into dentate gyrus granule cells in the hippocampus. Mediates Zn(2+) reuptake from the secreted milk within the alveolar lumen.
Synonyms: ZIP-3; ZIP3
Tractability: Antibody: its Gene Ontology location is reachable by antibodies, with high confidence; UniProt places it where antibodies can reach, with medium confidence; UniProt predicts a signal peptide or a membrane-spanning region. PROTAC: ubiquitination databases record sites on it.
Target class: Transporter
Gene: Protein-coding gene on chromosome 19 (2,732,204 to 2,740,070, reverse strand). Ensembl gene ENSG00000141873.
Subcellular location: Cell membrane; Apical cell membrane
Subcellular location (Human Protein Atlas): Vesicles
Pathways (Reactome):
Transport of small molecules: Zinc influx into cells by the SLC39 gene family
Gene Ontology:
Molecular function: zinc ion transmembrane transporter activity; metal ion transmembrane transporter activity
Biological process: zinc ion import across plasma membrane; zinc ion transmembrane transport; metal ion transport; transmembrane transport
Cellular component: apical plasma membrane; hippocampal mossy fiber to CA3 synapse; plasma membrane; membrane
Genetic constraint (gnomAD): Loss-of-function variants: 3 observed, 7.25 expected, observed/expected ratio (o/e) 0.41, 90% interval 0.19 to 1.07. That is too few expected variants to judge how well the gene tolerates losing a copy. Missense variants: 412 observed, 442.22 expected, observed/expected ratio (o/e) 0.93, 90% interval 0.86 to 1.01. Synonymous variants: 250 observed, 224.7 expected, observed/expected ratio (o/e) 1.11, 90% interval 1 to 1.24.
Homologues: Orthologues: chimpanzee SLC39A3 (100% identical), macaque DIRAS1 (99% identical), dog SLC39A3 (92% identical), guinea pig SLC39A3 (88% identical), rat Slc39a3 (84% identical), mouse Slc39a3 (84% identical), tropical clawed frog slc39a3 (67% identical), Drosophila melanogaster Zip42C.1 (28% identical), Caenorhabditis elegans zipt-3 (26% identical). Paralogues in human: SLC39A1 (32% identical), SLC39A2 (27% identical).
Diseases named in the same sentence as SLC39A3 in open-access papers:
SLC39A3 is named in the same sentence as 14 diseases in open-access papers, as found by Europe PMC text mining. Sharing a sentence is not in itself a finding about the gene and the disease. The quoted sentences say what the papers report.
pancreatic cancer (2 papers, 2021). "Recent studies have suggested that low SLC39A1, SLC39A2 and SLC39A3 expression in prostate cancer, low SLC39A3 and high SLC39A4 expression in pancreatic cancer." (PMID 34615436, 2021).
prostate carcinoma (2 papers, 2020 to 2021). A carcinoma that arises from epithelial cells of the prostate gland. "Low levels of Zn have been detected in serum and tumor tissues of patients with prostate cancer, and downregulated expression of SLC39A1, SLC39A2 and SLC39A3 has been demonstrated." (PMID 32744318, 2020).
bipolar disorder (1 paper, 2019). A disorder of the brain that causes unusual shifts in mood, energy, activity levels and the ability to carry out day-to-day tasks. "For example, SLC39A3 is associated with bipolar disorder according to GWAS analyses." (PMID 31533672, 2019).
bladder cancer (1 paper, 2025). "We identified a novel association between lower circulating expression of SLC39A3 and bladder cancer risk." (PMID 39789109, 2025). "TWAS identified four genes for which expression levels were associated with bladder cancer risk: SLC39A3 (OR = 0.91, CI = 0.87–0.95, FDR = 0.015), ZNF737 (OR = 0.91, CI = 0.88–0.95, FDR = 0.016), FAM53A (OR = 1.09, CI = 1.05–1.14, FDR = 0.022), and PPP1R2 (OR = 1.09, CI = 1.05–1.13, FDR = 0.049)." (PMID 39789109, 2025). "Higher whole blood expression of FAM53A and PPP1R2 was associated with higher odds of bladder cancer, while higher expression of SLC39A3 and ZNF737 was associated with lower odds of bladder cancer." (PMID 39789109, 2025). "A total of four genes (SLC39A3 on 19p13.3, ZNF737 on 19p12, FAM53A on 4p16.3, and PPP1R2 on 3q29) were identified to be associated with bladder cancer risk with FDR < 0.05." (PMID 39789109, 2025). "For example, a pan-cancer TCGA analysis found that tumor overexpression of SLC39A3, SLC39A5, and SLC39A11 was associated with better overall survival after bladder cancer diagnosis, whereas tumor overexpression of SLC39A2, SLC39A8, SLC39A9, and SLC39A14 was associated with poorer survival." (PMID 39789109, 2025). "We did not identify any GWAS-identified bladder cancer risk SNPs located within 1 Mb of SLC39A3, ZNF737, and PPP1R2." (PMID 39789109, 2025).
lymph node metastasis (1 paper, 2020). "For patients with positive lymph node metastasis, SLC39A2, SLC39A3, SLC39A7, SLC39A8, SLC39A12 and SLC39A13 high expression suggested a worse OS, but SLC39A10 high expression suggested a benefit OS." (PMID 32744318, 2020).
schizophrenia (1 paper, 2020). A major psychotic disorder characterized by abnormalities in the perception or expression of reality. "All but two (slc39a3 and nutf2l) of these differentially expressed genes have one (or more) known human orthologues, many playing a role in functional pathways relevant to schizophrenia (see Discussion)." (PMID 32015324, 2020).
cancer (4 papers, 2020 to 2025). A tumor composed of atypical neoplastic, often pleomorphic cells that invade other tissues. "The hub genes ATP6AP2, ACTR1A, SYNM, ZMYND8, CAMTA1, SLC39A3, and DHCR24, are associated with cancer development and progression." (PMID 39757707, 2025).
tumor (4 papers, 2020 to 2025). "Both the sarco-sphere model as well as the corresponding tumor tissue harbored an in-frame EIF5A::USP6 fusion in chromosome 17, homozygous losses of CDKN2A/B and ATRK, a truncation in the NOTCH1 gene and a TCF3::SLC39A3 rearrangement." (PMID 37951844, 2024). "It is noteworthy that the SLC39A2, SLC39A3, SLC39A3, and SLC39A5 showed a significant negative correlation with the macrophages and neutrophil cell infiltration in most tumor types." (PMID 34925450, 2021).
SLC39A3 also shares sentences with these, for which no sentence is quoted: age (1 paper); connective tissue diseases (1); gastric adenocarcinoma (1); lung squamous cell carcinoma (1); myopathy (1); neurological disease (1).